ENSG00000282807 (novel transcript)
Gene: Long non-coding RNA gene on chromosome 19 (71,006 to 72,719, forward strand). Ensembl gene ENSG00000282807.
Gene Ontology:
Biological process: miRNA-mediated post-transcriptional gene silencing